INS (insulin)
Diseases named in the same sentence as INS in open-access papers (continued):
Sharing a sentence is not in itself a finding about the gene and the disease.
diabetes (continued). "The amounts of 21 food groups were divided into quartiles and adjusted for age, energy intake, current smoking, current alcohol use, physical activity, diabetes duration, use of oral hypoglycemic agents as well as insulin use, and sex." (PMID 35893888, 2022). "Most pharmacological interventions for the treatment of diabetes rely on promoting insulin secretion or supplementing insulin to regulate blood sugar." (PMID 36187097, 2022). "Hypertriglyceridemia is a condition very commonly found in patients suffering from diabetes mellitus and is also seen in situations of insulin resistance either due to reduced catabolism or reduced production of lipoproteins." (PMID 35528161, 2022). "MODY is monogenic diabetes caused by a single gene mutation of either HNF-1α, HNF-1β, HNF-4α, HNF-1β, glucokinase, PAK4, KLF11, neurogenic differentiation 1 (neuroD1), and insulin (INS)." (PMID 35956399, 2022). "So far, treating diabetes has involved giving patients insulin injections and oral antidiabetic medications." (PMID 36465856, 2022). "The most important risk variables related with the development of DR in diabetes were found to be age, gender, previous family history of DM, longer duration of diabetes, being on Insulin treatment alone, and higher systolic blood pressure." (PMID 36262700, 2022). "In type 2 diabetes mellitus, formation of Reactive Oxygen Species (ROS) resulted from impaired insulin synthesis due to pancreatic β-cell death by apoptosis." (PMID 35620596, 2022). "The beneficial effect of EEI on insulin resistance and diabetes is mediated by the insulin signaling pathway and inflammatory response." (PMID 36432581, 2022). "Diabetes mellitus is a group of metabolic disorder characterized by high blood glucose levels that results from defects in insulin secretion, action, or both." (PMID 36227943, 2022). "Based on CGM glucose data alone, this is one of the largest glucose datasets available from individuals with insulin-requiring diabetes." (PMID 35565875, 2022). "Diabetes mellitus (DM) is a metabolic disease characterized by hyperglycemia due to impaired insulin secretion or impaired insulin function." (PMID 35692502, 2022). "Studies that used animal models to analyse and evaluate the role of zinc (Zn) in diabetes progression have revealed that zinc (Zn) has shown a consistent role in the insulin secretion while improving the sensitivity of insulin." (PMID 35807813, 2022). "Models were trained for age, sex, HbA1c, insulin sensitivity, BMI, prediabetes, and the occurrence of diabetes." (PMID 36572938, 2022). "Therapeutic intervention by insulin and amylin-based peptides to regulate blood glucose metabolism in diabetes is thus a logical mimic of the endogenous system." (PMID 35335929, 2022). "Previously, xenogeneic insulin from pigs has been adopted for human diabetes treatment for more than 60 years because of the amino acid similarity of porcine insulin to human insulin." (PMID 36090775, 2022). "In contrast, milk insulin concentration was observed to be lower in women with a history of type 1 or 2 diabetes compared with a control group." (PMID 35277026, 2022). "In summary, these data indicate that the glucose-lowering effect of sacubitril/valsartan, as evidenced by a small but significant reduction in HbA1c and new use of insulin, was similar in heart failure patients with diabetes across the spectrum of LVEF." (PMID 35717169, 2022). "The Endocannabinoid system (ECS) participates in the development of obesity and diabetes mellitus through varying consistent factors including glucose metabolism, lipid metabolism, and insulin sensitivity." (PMID 36159331, 2022). "One article defined T2DM as self-reported physician-diagnosed diabetes, or use of oral hypoglycemic drugs or insulin." (PMID 35805265, 2022).
diabetes (continued). "Specific DPP-IV inhibitors (gliptins) are currently used in patients with type 2 diabetes mellitus to promote insulin secretion by prolonging the activity of the incretins glucagon-like peptide 1 (GLP-1) and glucose-dependent insulinotropic polypeptide (GIP)." (PMID 35565202, 2022). "Direct differentiation can be used to generate insulin-secreting cells from human induced pluripotent stem cells (hiPSC) from patients with diabetes." (PMID 35740935, 2022). "This raises questions about how persons experience a life with insulin treated diabetes and their ability to be reconciled with the changes in life that diabetes cause." (PMID 35726172, 2022). "As insulin demand and prices rise dramatically, insulin affordability has increasingly become an issue facing patients with diabetes worldwide." (PMID 35546683, 2022). "The expression of the human costimulatory B7.1 molecule under the control of the rat insulin gene promoter as a transgene in these mice led to the development of diabetes." (PMID 35498419, 2022). "Studies have shown that type 2 diabetes mellitus, characterized by insulin resistance, is closely related to AD, which has drawn extensive attention to the relationship between hippocampal insulin signaling and AD." (PMID 36430894, 2022). "This information can be helpful when considering appropriate insulin dosing on admission as well adjusting outpatient diabetes medication management upon discharge." (PMID 35917098, 2022). "Diabetes mellitus (DM) is a metabolic disease characterized by the state of hyperglycemia as a result of a change in insulin secretion and action." (PMID 35767589, 2022). "The level of serum C-peptide level (which acts as a substitute for insulin) is a reliable and sensitive indicator for beta-cell activity; it can also be used to distinguish self-immune diabetes mellitus from the other subtypes of DM (diabetes mellitus)." (PMID 36420297, 2022). "Once IGT is established, we postulate it initiates a vicious spiral in which elevated plasma glucose impairs β-cell metabolism and insulin secretion further, causing greater hyperglycaemia and fuelling the progression of IGT to diabetes." (PMID 36376280, 2022). "Gregory (2019) emphasised the importance of training to ensure that community nursing staff are competent to deliver effective diabetes care, including insulin administration to people with intellectual disabilities." (PMID 35983585, 2022). "There are other variables that were significant in other studies but were found to be non-significant in this study, such as smoking, the duration of diabetes, gender, comorbidities, and treatments such as Insulin and Oral Anti-Diabetic Medication." (PMID 36361092, 2022). "Insulin resistance, the most prevalent cause of type 2 diabetes mellitus (T2DM), is caused by insulin signaling pathway dysregulation, which is caused by reduced insulin sensitivity." (PMID 36043008, 2022). "Stem cell-based therapies offer an alternative treatment option for diabetes through sequential differentiation of stem cells into beta cells that are able to react to blood glucose and consequently synthesize and secrete insulin." (PMID 35674918, 2022). "Many researchers report that the relationship between diabetes and dementia are involved in vascular alteration and impaired cerebral insulin signaling, leading to cognition." (PMID 35328405, 2022). "Insulin pump therapy represents an alternative to multiple daily injections and can improve glycemic control and quality of life (QoL) in Type 1 diabetes mellitus (T1DM) patients." (PMID 35915454, 2022). "This trial aims to evaluate the clinical efficacy of closed-loop insulin delivery throughout pregnancy in a larger sample, across multiple sites with varying levels of diabetes technology experience." (PMID 35382796, 2022). "The East African Diabetes Study Group (EADSG) advises starting insulin therapy even in newly diagnosed T2DM patients with symptoms and/or severe hyperglycemia." (PMID 35854336, 2022).
diabetes (continued). "The subjects had a median diabetes duration of 7 years, and 45% were users of insulin alone or in combination with oral antidiabetic drugs." (PMID 35300751, 2022). "We included several potential confounders in the analysis, like BP, BMI, insulin use, Hba1cand age of onset of diabetes." (PMID 34874549, 2022). "QOL outcomes were assessed using Insulin Dosing Systems: Perceptions, Ideas, Reflections, and Expectations, diabetes impact, and device satisfaction measures (with maximum scores of 100, 10, and 10, respectively) and semistructured interviews." (PMID 36279156, 2022). "The complexity of the therapeutic regime in diabetes, together with a lack of adequate knowledge, makes it very difficult for some people to adhere to the restrictions of living with insulin treated diabetes." (PMID 35726172, 2022). "In the mouse model, the circadian rhythm of the pancreas has been proven to play an important role in normal insulin release and glucose homeostasis, whereas mice with a disturbed pancreatic-islet circadian rhythm develop hypoinsulinemia and diabetes." (PMID 36700071, 2022). "It is important to appreciate the critical roles that school staff can play in diabetes management, from supporting children with their insulin shots to ensuring exercise and nutrition therapy." (PMID 36425875, 2022). "Genetic cooperation between the nucleus and mitochondria has been demonstrated to impact diabetes related phenotypes such as glucose metabolism and insulin sensitivity using mouse models." (PMID 36276935, 2022). "In this cross-sectional study of 2482 US adults with diabetes using insulin, the prevalence of glycemic control (glycated hemoglobin level <7%) remained unchanged (29.2% in 1988-1994 to 27.5% in 2017-2020)." (PMID 36538330, 2022). "Of note, recurrent patients with diabetes were treated with insulin at least twice as often as incident patients with diabetes, both before the hospital stay and at discharge." (PMID 35157710, 2022). "Patients with DR of any type had significantly more type 1 diabetes (p < 0.001), higher glycated hemoglobin (p < 0.001), longer duration of diabetes (p < 0.001), more insulin treatment (p < 0.001), and fewer oral antidiabetics (p < 0.001)." (PMID 35268409, 2022). "Many preoperative patient factors, such as age, the use of insulin, body mass index (BMI), glycosylated hemoglobin (HbA1C), diabetes duration, fasting c-peptide level, and medication usage were associated with T2DM remission." (PMID 36289529, 2022). "In patients with ESKD, around 30% had “burn-out diabetes” who required reduction or discontinuation of insulin treatment and OGLDs." (PMID 35528010, 2022). "Severe diabetes in obese ZDF rats revealed a significant decrease in insulin levels when compared with mildly diabetic animals in an age-dependent manner." (PMID 36290422, 2022). "Although both of these processes improve insulin sensitivity, the impact of Cr3+ on insulin resistance in diabetics and those with MeS is contentious." (PMID 35268685, 2022). "The effects of hyperglycemia on insulin secretion can vary depending on the phase of diabetes development." (PMID 35743160, 2022). "Zidovudine exhibited phase 4 for diabetes mellitus/insulin sensitivity, CVD/metabolic diseases, and various inflammation/infection-related diseases." (PMID 35935642, 2022). "Type 2 diabetes mellitus (T2DM) is a metabolic disorder due to defects in insulin secretion or insulin resistance leading to the dysfunction and damage of various organs." (PMID 36589820, 2022). "Diabetes mellitus (DM) is a metabolic disorder characterized by a high blood sugar level resulting from defects in insulin secretion, insulin action, or both." (PMID 35294449, 2022). "Diabetes mellitus is an endocrine metabolic condition characterized by high blood sugar levels, insulin resistance, and ineffective insulin secretion." (PMID 36144587, 2022).
diabetes (continued). "Diabetes mellitus (DM) is a chronic, metabolic disease in which blood sugar levels increase due to insulin hormone disorders: one of which is hyperglycemia." (PMID 35392260, 2022). "Nonetheless, the promotion of glucose‐dependent insulin secretion, coupled with reduced glucagon release, represents an ideal paradigm for diabetes therapy." (PMID 33822370, 2022). "Type 2 diabetes mellitus (T2DM) is a condition wherein insulin secretion becomes inadequate and is generally a disease of aging." (PMID 35747025, 2022). "Though crowdfunding can temporarily increase access to insulin, ethical issues related to crowdfunding for diabetes care exist." (PMID 35436214, 2022). "Diet therapy, pharmacology, and insulin therapy are the basic treatment approaches for diabetes control, along with a large range of glucose-lowering medications that exert hypoglycemic effects through diverse mechanisms." (PMID 35624887, 2022). "Recovery of first-phase insulin release was seen in individuals with diabetes remission, which was durable at one year." (PMID 35806437, 2022). "The systematic search was conducted using the following Medical Subject Heading (MeSH) terms “Moringa oleifera”, “diabetes mellitus”, “glucose metabolism”, “insulin resistance”, “oxidative stress”, and “inflammation” as well as relevant synonyms." (PMID 35899107, 2022). "Among the diabetes-related parameters, we found BMI to be the most relevant factor for increasing the risk of prediabetes and T2DM except fasting glucose, insulin, HOMA-IR score, and HbA1c through stepwise linear regression analysis." (PMID 35740093, 2022). "Hypoglycaemia is a common side effect of insulin and some other antihyperglycaemic agents used to treat diabetes." (PMID 34704120, 2022). "The belief that insulin therapy is necessary for controlling diabetes impacts patients’ willingness to accept insulin.“Because my condition requires injection." (PMID 35172774, 2022). "In contrast, antioxidant treatment using butylated hydroxyanisole or supplementation with reducing agents can improve proinsulin folding and promote insulin granule formation in diabetes models." (PMID 35204835, 2022). "The mean (SD) time since diabetes diagnosis was 12.5 (9.0) years, and 142 patients (59.4%) used insulin at baseline." (PMID 36374502, 2022). "A ketogenic diet (KD) is an effective approach to treat diabetes by regulating blood glucose and insulin levels." (PMID 36355132, 2022). "Diabetes affects zinc homeostasis in many ways, and zinc plays a definite role in the synthesis, storage, and secretion of insulin." (PMID 35682762, 2022). "Several pieces of preclinical evidence revealed that pyruvate protected from diabetic cataract and retinopathy and increased blood insulin levels." (PMID 35991638, 2022). "The glucostatic cycle is dysregulated in the diabetes mellitus, due to an insufficient number of β-cells that need to produce the required amount of insulin according to the fasted and postprandial states in order to maintain normoglycemia." (PMID 35806376, 2022). "In the past, insulin injections were given subcutaneously to treat diabetes due to low oral bioavailability in the gastrointestinal (GI) tract." (PMID 36559303, 2022). "Insulin secretagogues lower blood glucose by promoting insulin secretion, boosting insulin levels in the blood, and thereby managing diabetes." (PMID 36557959, 2022). "Such a notion helps in explaining our finding on the significant reduction in ID in patients with diabetes taking insulin injections." (PMID 35334901, 2022). "One study indicated having a history of diabetes with insulin injection for more than 5 years as an inclusion criterion." (PMID 36614864, 2022). "Several diabetes-related complications, including glucose and insulin imbalances as well as the microvascular and macrovascular comorbidities, were found to significantly predispose patients to the progression of MCI and its conversion to dementia." (PMID 35682821, 2022).
diabetes (continued). "Insulin therapy is the mainstay of treatment for those who have diabetes mellitus type 1 or type 2 with advanced disease." (PMID 35443846, 2022). "Regarding the acceptability of diabetes medicines available in their context, there were isolated responses that indicated some participants’ preference for oral medicines over injectable insulin." (PMID 36962297, 2022). "Iron overload can lead to diabetes symptoms such as decreased insulin secretion, metabolic abnormalities, and mitochondrial dysfunction, and accelerate the development of diabetes with prompting β cell dysfunction." (PMID 35874833, 2022). "In patients with diabetes, long-term hyperglycemic status results in β-cell insulin desensitization and failure, also termed glucose toxicity." (PMID 35841066, 2022). "There is a positive relationship between serum insulin and elevated serum urate levels in healthy individuals and people with diabetes." (PMID 36483739, 2022). "In this review, 11 publications were identified to explore the barriers and facilitators to managing diabetes with insulin in people with intellectual disabilities." (PMID 35983585, 2022). "More recently, a secondary analysis from the D2d trial (comparing VitD with placebo for the prevention of type 2 diabetes mellitus) investigated the effects of VitD3 supplementation on insulin sensitivity and β-cell function." (PMID 36014761, 2022). "Several studies have explored the effect of TRE on patients with diabetes and prediabetes, and demonstrated that TRE has the beneficial effects on 24-h plasma glucose, insulin sensitivity, weight loss, and glucose tolerance." (PMID 36407528, 2022). "These species are also as known “insulin plant” because local communities use the infusions of various organs of these plants empirically to treat diabetes." (PMID 36558108, 2022). "This trial established the need for an adequate basal-bolus insulin regimen, capillary blood glucose monitoring, carbohydrate counting, and diabetes education for T1D, now recommended by national and international guidelines." (PMID 36219199, 2022). "When diabetes mellitus type 2 impacts insulin resistance, at first, the pancreas releases increased levels of insulin in order to compensate." (PMID 35453527, 2022). "Insulin, which is secreted by pancreatic β-cells, plays a crucial role in the occurrence and development of diabetes." (PMID 35893885, 2022). "Progressive loss of pancreatic β-cell functional mass and anti-diabetic drug responsivity are classic findings in diabetes, frequently attributed to compensatory insulin hypersecretion and β-cell exhaustion." (PMID 35180212, 2022). "Despite the great progress made in the treatment of diabetes with insulin and conventional antidiabetic drugs, their therapeutic results are still far from perfect." (PMID 35899227, 2022). "Diabetes mellitus (DM) is characterized by high blood sugar levels that are accompanied by impaired carbohydrate, lipid, and protein metabolism as a result of insulin function insufficiency." (PMID 36510592, 2022). "Impaired metabolic control due to hypothalamic insulin dysfunction is, therefore, proposed to be one of the links between diabetes and brain dysfunction in AD." (PMID 36232867, 2022). "Medication-related factors that affected glycemic control involved the drug regimen of Glibenclamide and metformin, route of administration, number of anti-diabetics, number of other daily regular drugs, insulin use, and the diabetes treatment regimen." (PMID 35891859, 2022). "Diabetic ketoacidosis (DKA) is one of the most severe acute complications of type 1 diabetes mellitus (T1DM), an autoimmune disease characterized by an absolute deficiency of insulin and resultant hyperglycaemia." (PMID 36460989, 2022). "The role of islet cell types in the pathogenesis of diabetes, glucose levels, and insulin production has been thoroughly researched and documented, be it alpha cells, beta cells, or delta + gamma cells." (PMID 36232752, 2022).